TNF (tumor necrosis factor)
Diseases named in the same sentence as TNF in open-access papers (continued):
Sharing a sentence is not in itself a finding about the gene and the disease.
tumor (continued). "In addition, CD8+ T cells can also secrete cytokines, such as IFN-γ and TNF-α, which directly inhibit tumour cell growth and proliferation." (PMID 38130720, 2023). "However, in other contexts, TNF-α promotes tumor growth and creates a tumor-supportive microenvironment, ultimately facilitating tumor growth and progression." (PMID 38155968, 2023). "For example, TNF-α at high concentrations can kill EC tumor cells." (PMID 37927462, 2023). "Furthermore, the concentration of cytotoxic cytokines IFNγ and TNFα in tumor tissues also significantly increased in the 8FNs groups." (PMID 37162249, 2023). "Importantly, knockdown of TNF-α with RNA interference prevented the synergistic anti-tumor effect of tolinapant combined with entinostat." (PMID 36831656, 2023). "TNF is required for the exposure of phosphatidylserine on the surface of tumor cells." (PMID 36982826, 2023). "We here describe a potency-matched dual-cytokine antibody fusion protein containing a tumor-targeting antibody fragment specific to human fibroblast activation protein (FAP), simultaneously linked to both interleukin-2 (IL2) and a tumor necrosis factor (TNF) mutant." (PMID 37092450, 2023). "Interestingly, tumour cell derived TNFα induced the expression of the hepatocyte growth factor receptor (HGFR or Met) on neutrophils, which in response to HGF expressed the inducible nitric oxide synthase (iNOS) and NO to kill cancer cells." (PMID 37180120, 2023). "Additionally, the levels of IFN-γ and TNF-α in tumor tissues and blood were determined by flowcytometry and ELISA." (PMID 37919724, 2023). "TNF-α levels were elevated in tumor mice compared to the control group." (PMID 37033618, 2023). "Future studies should address whether inhibiting TNF in the TME or ablating TNF receptors on tumor cells will reverse neutrophil-derived resistance to monocyte targeted therapies in tumors with PN signature." (PMID 37012245, 2023). "TNF-α can have a pro- or antitumor effect depending on whether it is secreted by the tumor microenvironment or by the tumor cells themselves, so we suggest that the modulation of this cytokine by scorpion venom H. junceus favors its antitumor effect." (PMID 38137888, 2023). "The rates of ADR reports of infliximab-related gastrointestinal disorders, cardiac disorders, benign, malignant, and unspecified neoplasms, vascular disorders, and respiratory, thoracic, and mediastinal disorders were significantly higher than those of the other four TNFα inhibitors." (PMID 37554981, 2023). "Tumor-specific CD4+ T cell responses were dominated by tumor necrosis factor (TNF) production." (PMID 38299143, 2023). "In vivo, ASPS, ADP, ISAg, and ASP could increase the level of TNF-α in the serum of tumor-bearing mice." (PMID 37959774, 2023). "Lower circulating levels of TNF-α can stabilize tumor growth." (PMID 37711747, 2023). "In this investigation, a comparative study of the mRNA expression of NF-κB p65 (RelA) and TNFα in both 33 brain tumor samples and TCGA datasets has revealed that the transcriptional activity of these genes is significantly higher in tumor samples than in normal samples." (PMID 37892820, 2023). "Indeed, cytokines such as IFN-γ, IL-27, IL-23, IL-12, and IL-2 have tumor suppressor functions, whereas pro-inflammatory cytokines, including IL-1, IL-6, and tumor necrosis factor-α, have tumor-promoting." (PMID 37046658, 2023). "Additionally, mTORC1 signaling, glycolysis, TGF‐β signaling, PI3K/AKT/mTORC signaling, hypoxia, TNF-α signaling via NF-κB, and angiogenesis were enriched in tumor ECs, suggesting the involvement of EndMT ECs in angiogenesis induction in HPSCC." (PMID 37853464, 2023). "However, low adiponectin levels restrict inhibitory effect of TNF-α on tumor cell proliferation by inhibiting the production of TNF-α in macrophages." (PMID 37266440, 2023). "Lymphocytes produce important cytokines such as TNF‐α, inhibiting tumor growth." (PMID 36052483, 2023).
tumor (continued). "A possible mechanism is that circulating lymphocytes may promote cytotoxic cell death to exert anti-tumor effect by secreting cytokines such as interferon-gamma and tumor necrosis factor-alpha." (PMID 36969019, 2023). "It is well known that NK and CD8+ T cells could specifically kill the tumor cells through several common pathways, including perforin, granzyme, Fas/FasL, TNF-α, and IFN-γ." (PMID 36902617, 2023). "Genes such as Ado, TRAF2, Rb1cc1, PRMT1 and RIPK1 regulate tumor sensitivity to TNF-α." (PMID 37732732, 2023). "In general, in response to tumor ablation, numerous pro-inflammatory physiological pathways are activated, resulting in the upregulation of signaling molecules including IL(interleukin)-1β, IL-1α, IL-6, IL-8, IL-18, and TNFα (tumor necrosis factor α)." (PMID 36969248, 2023). "As TNF signaling suppresses the functions of CD8 and NK cells, which mediate anti-tumor effects, TNF inhibition may promote their functions, thereby leading to anti-tumor effects." (PMID 36996146, 2023). "In addition, TNF-α is also required for the induction and activation of cytotoxic T cells (CTLs), which are the most effective tumor-killing cells." (PMID 37679802, 2023). "However, the TNF network is also very complex and involved in the spreading of aggressive and resistant tumor cells, suggesting a dual role of vit-D3 in the regulation of pro-inflammatory pathways." (PMID 37835527, 2023). "In addition, TNF-α, a central mediator of free radical-induced oxidative stress and inflammatory reactions, activates NF-κB, and this induces tumor cells to secrete various cytokines, such as VEGF, MCF-1/CCL-2, IL-8, and COX-2." (PMID 37434755, 2023). "An in vivo murine model of OSCC with some animals having periodontitis-associated bacteria addition, demonstrated increased alveolar bone resorption in the addition group as well as increased tumour mass and tumour growth rate that paralleled the significant upregulation of TNF-α." (PMID 36980727, 2023). "Moreover, HDAC inhibition has been observed to reduce the responsiveness of tumor cells to TNF-alpha-mediated activation of the NF-kappa B pathway." (PMID 38001653, 2023). "In addition to being involved in the systemic inflammatory response, TNF-α is involved in the control of tumor growth." (PMID 36831404, 2023). "TNF-related interactions such as TNF_VSIR and CD74_MIF interactions are enriched in SN, exhibiting more inflammation-related tumor features." (PMID 37745301, 2023). "TNFα is present in tumor tissue and systemic anti-TNFα abrogates the effects of radiation in vivo." (PMID 36831373, 2023). "In contrast, in the tumor, the M1-polarizing cytokines iNOS, TNF-α, and INFγ are prominent." (PMID 37628775, 2023). "TNFα is also involved in the regulation of CRC-associated signals and pathways, such as the activation of reactive oxygen species, NF-κB and MAPK, which contribute to angiogenesis in the tumour microenvironment." (PMID 38041080, 2023). "Also important was the observation that a first dose of FAP-CAR T cells enhanced the activation of CD45.2+tdTomato+ Meso-CAR T cells in tumor sites, as demonstrated by increased expression of GzmB, TNF-α, and IFN-γ after stimulation." (PMID 37607999, 2023). "Because M. hyorhinis-induced TNF-α expression in PCa may promote advancement of tumor progression in vivo, we assessed the extent to which M. hyorhinis infection affected proliferation, invasion, and migration of PCa cells." (PMID 37867861, 2023). "On the other hand, inflammatory cells play a role in promoting tumor development by secreting a variety of inflammatory cytokines and chemokines, as well as proangiogenic factors (e.g., tumor necrosis factor, interleukin-1, interleukin-6, and vascular endothelial growth factor)." (PMID 35249158, 2023). "Similarly, multiple pathways implicated in PKD (e.g., IFN-γ/JAK-STAT, TNF-α, NF-κB, PI3K, and HIF-1) drive PD-L1 and CD80/CD86 expression on tumor cells." (PMID 37345660, 2023).
tumor (continued). "Bregs express IL-10, TGF-β, and TNF-α in most inflammatory and tumor microenvironments." (PMID 37432957, 2023). "TNF-α and IL-1β are essential pro-inflammatory cytokines found in tumor metastasis." (PMID 37895012, 2023). "Bifidobacterium can directly induce DC maturation and cytokine (IFNγ, TNFα, IL-10, IL-17) production, thus promoting anti-tumor immunity and anti-PD-L1 efficacy and almost inhibiting tumor progression after combination therapy with PD-L1 monoclonal antibody (mAb)." (PMID 37841431, 2023). "GSEA data also indicated that PFKP could participate in tumor immune regulation because of its close connection with the inflammatory response and TNF-α signaling via NF-κB hallmarks." (PMID 37833332, 2023). "TNF-α can selectively kill tumor cells, stimulate lymphocyte proliferation, and activate NK cells." (PMID 37958131, 2023). "Furthermore, this suggests that the observed anti-tumor effect and survival benefit in the combination group is at least in part due to host TNF-dependent mechanisms." (PMID 37055579, 2023). "Activation of the M1-like pathway is accompanied by a release of cytokines, including tumor necrosis factor α (TNF-α) and interleukin 1β (IL-1β), and IL-6, which facilitates a pro-inflammatory response in defense against pathogenic insults and malignant tumor cells." (PMID 38022518, 2023). "One of the effects of TNF is the initiation of apoptosis, including in tumor cells." (PMID 36672212, 2023). "Moreover, a research suggests that TNF-α, which is released by M1 type macrophages, plays a role in facilitating tumor progression." (PMID 38161335, 2023). "NK cells produce cytokines, such as IFN-γ and TNF-α, which have anti-tumor effects." (PMID 38283362, 2023). "Indeed, MUC1-targeting CAR Ms showed potent anti-tumor function by phagocytosis and secretion of pro-inflammatory cytokines such as IL-1β, IL-8, and TNFα in the presence of MUC1 expressing tumor cells from solid lung tumors or malignant pleural effusions." (PMID 38017494, 2023). "It has been shown that immunogenic DCs secrete substantial quantities of inflammatory cytokines, including TNF-α, IL-12, IL-6, and IL-8, which may improve the clinical outcomes of tumor patients." (PMID 37513975, 2023). "Due to the anti-tumor role of TNF-α and IL-12, the expression of LAPTM5 in macrophages could be a potential mechanism to improve ICB efficacy." (PMID 37492578, 2023). "Efficient tumor control correlated with the induction of high frequencies of neoepitope-reactive T cells measured by the presence of T cells that simultaneously produce TNFα and IFNγ upon neopeptide re-stimulation." (PMID 37720215, 2023). "The degree of bystander tumor cell lysis also increases with the addition of TNF-α and IFN-γ." (PMID 37754534, 2023). "In NSCLC, TAMs could promote tumor cell glycolysis by TNFα secretion and facilitate tumor hypoxia by increasing AMPK and PGC-1α, leading to decreased PD-L1 of tumor cells and T-cell infiltration in TME to cause immunotherapy resistance." (PMID 37090727, 2023). "Macrophages are adept at phagocytosis, and whether their phagocytosis of live tumor cells is enhanced upon blockade of TNFα, IL-1β, or IL-6 is unknown." (PMID 37461742, 2023). "However, only Tex showed a decreased capacity to degranulate (CD107a exposure upon restimulation), produce the inflammatory cytokines IFNγ and TNFα, and kill tumor cells." (PMID 36732507, 2023). "More studies evaluating the role and utility of circulating, hepatic, and tumor TNF-α, specifically in patients with NAFLD-associated HCC, are warranted in the future to better define the association between circulating TNF-α with hepatic TNF-α from both malignant and healthy hepatic tissues." (PMID 37958479, 2023). "In addition, pro-inflammatory cytokines, especially TNF and IL-6, are critical tumor promotors that trigger the development of CACs." (PMID 37275854, 2023).
tumor (continued). "While under normal conditions endothelial cells upregulate adhesion molecules such as ICAM-1, VCAM-1 and E-selectin in response to tumor necrosis factor (TNFα), IFNγ, and interleukin-1, angiogenic tumor ECs are anergic to such signaling, resulting in suppressed immune cell infiltration into tumors." (PMID 37060495, 2023). "However, only CISP resulted in the strongest increase of CD8 T cells, NK cells, M1 macrophage and anti-tumor cytokines including IL-6, IFNγ, IFNβ, TNFα and IFNα in LLC tumors." (PMID 37607938, 2023). "Similarly, the Drosophila dlg-induced tumor is sensitive to the Drosophila homologue Defensin, mediated by TNF signaling." (PMID 37518191, 2023). "On one hand, TNF-α may promotes angiogenesis and metastasis of tumor cells at low concentrations, and at high levels it may exert antitumor effects." (PMID 37563607, 2023). "This is further orchestrated by the secretion of various inflammatory players including transforming growth factor-β (TGF-β), tumor necrosis factor-α (TNF-α), interleukin (IL)-1, IL-6, and IL-8, all of which promote a tumor-supportive environment for OSCC progression." (PMID 36675138, 2023). "Because efficacy and safety of TNFα systemic therapy will depend on its selective delivery to the tumor microenvironment, initial in vivo experiments were performed to investigate RGD4C.TPA‐mediated TNFα gene delivery upon intravenous administration to tumor‐bearing mice." (PMID 37331004, 2023). "Evidence from the existing studies has suggested that LITs could upregulate TNF-α to drive inflammatory responses, immune responses, and tumor progression." (PMID 36831664, 2023). "In addition, important tumor pathways such as Wnt, MAPK, PI3K/AKT, TGF-beta, NF-kB, Notch, AMPK, JAK-STAT, PD-1/PD-L1, mTOR, Ras, TNF, HIF-1, ErbB are also associated with the risk score, and pathways and functions are correlated as well." (PMID 37884883, 2023). "The decrease in TNF-α levels in sera of animals with a tumor and treated with H. junceus scorpion venom could be due to the fact that previous results suggest that this venom is capable of blocking voltage-gated sodium channels 1,5." (PMID 38137888, 2023). "TNF-α promotes tumor angiogenesis and accelerates tumor metastasis, but the molecular mechanisms remain unclear." (PMID 37869102, 2023). "TNF-α, predominantly secreted by macrophages, is a cytokine with tumor necrotic activity." (PMID 37893697, 2023). "For instance, the tumor necrosis factor ligand superfamily member 10 (TNFSF10), also known as TRAIL, encodes a cytokine that belongs to the tumor necrosis factor (TNF) ligand family, it preferentially induces apoptosis in transformed and tumor cells and was proposed as a prognostic indicator of PC." (PMID 37035749, 2023). "The production of TNF‐α and TRAIL renders tumor cells susceptible to IAPi." (PMID 37132167, 2023). "TNF-α participates in the destruction of tumor cell structure and the induction of cell apoptosis and may serve as a co-stimulatory factor for mitogen-activated normal B cells." (PMID 37764221, 2023). "Indeed, they showed that the encounter with the cognate antigen on tumor cells unleashed the release of TNFα by IgE-presensitized MCs, eventually inducing apoptosis in tumor cells." (PMID 37376140, 2023). "Thus, proinflammatory cytokines, such as TNF-α and IL-1, are induced in target organs of rodents by treatment with chemical tumor promoters." (PMID 37097392, 2023). "Proinflammatory M1‐like markers, such as CD80, TNFα, CXCL10, tend to be associated with an antitumor immune response, while macrophages expressing other proinflammatory cytokines (IL‐1β, IL‐6) can mediate tumor cell migration and cancer progression." (PMID 38037545, 2023). "Aggregated neutrophils can also create OSM when monocyte-derived TNF and tumor-derived soluble factors interact, which may contribute to cancer spread and disease progression in HCC." (PMID 37511228, 2023).
tumor (continued). "Several cytokines may contribute to tumor progression, particularly IL-1β, TNFα, and IL-6 play key roles in promoting and enhancing EMT." (PMID 37371856, 2023). "Moreover, we found a significantly higher positive regression coefficient between CD8A expression and TNF‐α or LTβ in adjacent tumour tissues than in HCC tissues and normal tissues." (PMID 37997519, 2023). "Furthermore, FLT3 ligand (Flt3L) production by NK cells enhances cDC1 proliferation and survival in the TME, whilst IFN-γ and TNFα secretion by NK cells increased tumor antigen cross-presentation by cDC1s." (PMID 37190135, 2023). "TNF-α upregulates the expression of PD-L1, and its control is indicative of tumour cell behaviour." (PMID 38137361, 2023). "In addition, when comparing blood sera from KPC tumor-bearing mice to sera from tumor-free control mice, we observed that circulating TNF-α protein levels increased in tumor-bearing mice." (PMID 37749321, 2023). "Hence, when over-secreted, TNF-α can be an endogenous tumor promoter, and trigger stages of cancer initiation and progression, involving angiogenesis and metastasis." (PMID 37507468, 2023). "ICAM-1 is a molecule whose expression is controlled by the cytokines TNF-α and IL-β, which plays an important role in colorectal pathogenesis, participating in mutual interactions between the tumor and extracellular matrix in signal transduction and numerous immune processes." (PMID 37569878, 2023). "Interestingly, this was dependent on the highly specific therapeutic responsiveness of the tumor types observed upon different therapeutic regimens tested in vitro and in vivo (TNFα, ASA, or EDPM)." (PMID 36980669, 2023). "PMs can be switched to tumor-associated macrophages (TAMs) in ascites with pro-tumor effect by releasing various soluble mediators, including IL-6, IL-10, CCL18, CCL22, TNF-α, TGF-β, and EGF that triggers pro-tumorigenic signaling pathways in tumor cells and infiltrating leukocytes in the TME." (PMID 37932814, 2023). "In the presence of TNF-α, the SMs had a heightened anti-tumor effect." (PMID 36831656, 2023). "Inflammation plays an important role in tumor progression: inflammatory responses stimulate tumor-associated macrophages to secrete cytokines, such as TGF-β and TNF-α, and promote tumor-cell metastasis; a persistent inflammatory response also leads to T-cell exhaustion and further tumor progression." (PMID 37107702, 2023). "Gene expression studies of TAMs treated with ruxolitinib showed that mammary tumor cells activate the JAK/STAT pathway in TAMs via secreted soluble factors, and thereby activate several tumor promoting pathways such as the TNF signaling pathway, PI3-Akt signaling pathway, VEGF signaling pathway." (PMID 37005447, 2023). "Furthermore, an increase of a series of cytokines (including IL-2, IFN-γ, and TNF-α) promotes lymphocyte proliferation and subsequently affects tumor deterioration." (PMID 37345200, 2023). "After antibiotics-mediated commensal reduction, tumor-infiltrating myeloid cells reacted unsuccessfully to CpG-oligonucleotide tumor immunotherapy resulting in lower TNF production, or to oxaliplatin treatment with diminished formation of reactive oxygen species as well as impaired cytotoxicity." (PMID 37511612, 2023). "Finally, cytokines measurement showed, in tumor mass of αPD-L1-treated mice, an increased level of cytokines known to exert anti-tumoral actions such as TNF-α, IFN-γ, and IL-6, and a concomitant decrease of the immune-suppressive cytokine IL-10." (PMID 36854895, 2023). "M1 macrophages are usually considered to be pro-inflammatory and anti-tumor, as they can secrete nitric oxide, tumor necrosis factor, and other effector molecules that kill bacteria and intracellular pathogens, as well as participate in inflammation and tissue damage." (PMID 38283752, 2023). "Such an effect of TNF on tumor cells is likely mediated by TNFR2." (PMID 36923938, 2023).